INS (insulin)
Diseases named in the same sentence as INS in open-access papers (continued):
Sharing a sentence is not in itself a finding about the gene and the disease.
Insulin resistance (continued). "Our findings demonstrate that aerobic exercise improves glucose uptake, glucose homeostasis, and insulin sensitivity in skeletal muscle, which is consistent with our hypothesis that regular exercise would mitigate the metabolic disruptions caused by obesity-induced insulin resistance." (PMID 40070461, 2025). "In conclusion, HXJT improves insulin resistance, enhances insulin sensitivity, and helps preserve glucose homeostasis." (PMID 41181590, 2025). "The mathematically developed Homeostatic Model Assessment Insulin Resistance (HOMA-IR) is the most commonly used method for assessing insulin resistance, based on fasting glucose and insulin levels." (PMID 40430120, 2025). "Biomarkers such as CRP, IL-6, and TNF-α serve as indicators of inflammation, while HOMA-IR, fasting insulin, and HbA1c are essential for evaluating insulin resistance." (PMID 40002771, 2025). "Studies have demonstrated that anthocyanins can exert hypoglycemic effects by improving insulin resistance, protecting β-cells, increasing insulin secretion, and reducing sugar digestion in the small intestine." (PMID 41227632, 2025). "Following treatment, a reduction in insulin levels and Homeostatic Model Assessment for Insulin Resistance (HOMA-IR) index, improved lipid profile, decreased triglycerides and total cholesterol, and increased HDL-C were described." (PMID 40362796, 2025). "The mouse model used in the current study exhibited systemic insulin resistance and impaired insulin secretion with attenuated beta cell expansion, making it a preferred translational model to investigate GDM." (PMID 40636710, 2025). "Together, these results suggest that both HIIT and MICT can alleviate high-fat-induced hyperlipidemia, glucose intolerance and insulin resistance with HIIT exhibiting superior efficacy on insulin sensitivity." (PMID 40305497, 2025). "Our data aligns with previous research, supporting the notion that TNFα induces insulin resistance by impairing insulin signaling and reducing glucose uptake in adipocytes." (PMID 39269560, 2025). "Our data identify a new locus of insulin resistance, characterized by insulin-independent mislocalization of GLUT4 and IRAP." (PMID 40631311, 2025). "Over time, this can lead to endothelial cell insulin resistance and reduced insulin secretion, and ultimately T2DM." (PMID 40149950, 2025). "The treatment of T2DM is challenging due to the side effects of oral hypoglycemic drugs and the limited efficacy of long-term insulin therapy, which can lead to insulin resistance (IR)." (PMID 39912972, 2025). "The development of insulin resistance is primarily attributed to proinflammatory cytokine responses in insulin-responsive tissues, particularly the liver and adipose tissue." (PMID 39859525, 2025). "Insulin resistance is a metabolic condition where tissues are resistant to the action of insulin, requiring higher-than-normal insulin concentrations to manage glucose." (PMID 39940348, 2025). "The HOMA index, calculated according to the formula by Matthews, used to assess the impact of both treatments on insulin resistance, showed that only the White Mulberry combination led to an improvement in insulin sensitivity." (PMID 40732887, 2025). "Surgery initiates a series of stress physiological processes in the body, inducing transient insulin resistance, which is related to a reduction in the efficacy of insulin to exert its normal anabolic actions." (PMID 40823584, 2025). "Under conditions of chronic low-grade inflammation, monocytes are activated and release pro-inflammatory cytokines, which contribute to insulin resistance by impairing insulin signaling pathways in peripheral tissues." (PMID 40357304, 2025). "Although oxidative stress plays a major role in the mechanisms of insulin resistance, and empagliflozin appears to mitigate oxidative stress, this is unlikely the primary mechanism for improved insulin sensitivity in HFpEF." (PMID 40281528, 2025).
Insulin resistance (continued). "Aging individuals (over 65 years old) are susceptible to developing type 2 diabetes, and these people present with insulin resistance that eventually leads to defects in insulin secretion." (PMID 40298742, 2025). "In the liver, IR presents as “selective hepatic insulin resistance”: insulin’s ability to suppress gluconeogenesis is diminished, resulting in fasting hyperglycemia, whereas its stimulatory effect on DNL remains intact or even enhanced." (PMID 41001677, 2025). "In animal models, MOTS-c enhances insulin sensitivity in skeletal muscle while protecting against diet-induced obesity and insulin resistance." (PMID 40507468, 2025). "Biological sex affects type 2 diabetes traits, including adiposity, insulin resistance and insulin secretion." (PMID 40768044, 2025). "In particular, the TG/HDL ratio has been confirmed in the literature as a marker of insulin resistance and of endothelial dysfunction in adults and children, and is correlated with BMI and reduced insulin sensitivity." (PMID 40078195, 2025). "These lipid intermediates act as activators of PKCε, which in turn dephosphorylates AKT and disrupts insulin signaling and thus leads to insulin resistance." (PMID 41220583, 2025). "Insulin resistance leads to diminished insulin action in the liver, muscle and adipose tissue and failure to maintain peripheral glucose homeostasis." (PMID 40583967, 2025). "The accumulation of lipids in insulin-responsive tissues is considered a key driver of lipid-induced insulin resistance." (PMID 41125144, 2025). "Fasting insulin levels in plasma and the homeostatic model assessment of insulin resistance (HOMA-IR) index were also decreased in the AAV-hGULL/mGULL group." (PMID 40955662, 2025). "Insulin resistance, characterized by reduced cellular responsiveness to insulin in tissues such as skeletal muscle, adipose tissue, and liver, disrupts metabolic homeostasis and significantly impacts the lymphatic vasculature." (PMID 41403736, 2025). "Gerald Reaven established and popularized his concept in his Banting Lecture that a defect of insulin-assisted glucose uptake, known as insulin resistance, is the source of many human diseases." (PMID 41514592, 2025). "Type 2 diabetes is characterized by insulin resistance and impaired insulin secretion, resulting from beta-cell dysfunction." (PMID 41155632, 2025). "In muscle, insulin resistance comprises both a shift in the insulin dose response and a reduction in the maximal effect of insulin to stimulate glucose uptake." (PMID 40631311, 2025). "The glycation of insulin by MGO contributes to insulin resistance by impairing glucose uptake and reducing insulin clearance." (PMID 40002398, 2025). "HIIT has been shown to effectively reduce hepatic insulin resistance and improve early-phase insulin secretion in individuals with type 2 diabetes, leading to significant reductions in fasting plasma glucose (FPG) levels." (PMID 39977858, 2025). "Insulin resistance was significantly increased in the disease group, as evidenced by elevated insulin levels and homeostatic model assessment of insulin resistance (HOMA-IR) values." (PMID 41309777, 2025). "This action helps lower blood insulin levels, essential in preventing insulin resistance and obesity." (PMID 40362352, 2025). "Diets with a high glycemic load and elevated fat content induce exaggerated postprandial glucose and insulin responses, promoting the development of insulin resistance." (PMID 40864811, 2025). "It works by reducing intestinal glucose uptake, decreasing metabolism in organ and tissues, increasing insulin secretion, and improving insulin resistance." (PMID 40083886, 2025). "Female KO mice, however, had higher fasting blood glucose and serum insulin levels suggesting the presence of mild insulin resistance." (PMID 37961647, 2025). "These factors collectively contribute to impaired insulin secretion and increased insulin resistance, resulting in post-transplant dysglycemia." (PMID 40995094, 2025).
Insulin resistance (continued). "Two main characteristics of T2DM are inadequate insulin secretion by β-cells and insulin resistance." (PMID 39136514, 2025). "This indicated that high-dose xylose-oligosaccharide can improve insulin sensitivity and reduce insulin resistance in T2D mice." (PMID 40565702, 2025). "Homeostasis model assessment of insulin resistance (HOMA-IR) provides a convenient measure to estimate insulin resistance from fasting insulin and glucose, which is necessary for the diagnosis and management of T2DM." (PMID 40978826, 2025). "These inflammatory mediators have been shown to impair insulin signaling, increase insulin resistance, and exacerbate hyperglycemia." (PMID 41296433, 2025). "These benefits arise through various mechanisms, including increased insulin‐mediated glucose uptake rates, improved glucose tolerance, and reduced insulin resistance." (PMID 40777199, 2025). "In the early stage of insulin resistance, compensatory hyperinsulinemia maintains the blood glucose levels within the physiological range by stimulating increased insulin secretion from pancreatic β-cells." (PMID 41514592, 2025). "We extended these studies to mice, and show that mice injected with low doses of insulin when fasting develop insulin resistance with impaired glucose tolerance and increased HOMA‐IR index." (PMID 39471069, 2025). "Among others, these changes include increased insulin resistance, altered carbohydrate metabolism, and increased insulin production." (PMID 41333061, 2025). "Elevated VF is strongly associated with insulin resistance, a key factor in the development of T2DM, as it releases pro-inflammatory cytokines that disrupt insulin signaling and exacerbate metabolic dysfunctions." (PMID 40607228, 2025). "Elevated insulin levels during insulin resistance can disrupt spermatogenesis and reduce male fertility." (PMID 40933264, 2025). "Insulin resistance in muscle and liver and impaired insulin secretion by pancreatic β cells are the core of T2D defects." (PMID 41012462, 2025). "Overall, insulin resistance (defined as 2 h insulin >80 mU/mL) was present in 44.5% of the participants." (PMID 40868057, 2025). "Overexpression of SOCS inhibits the insulin signaling system by blocking the binding of insulin receptor substrates (IR) to the insulin receptor (IR), leading to insulin resistance." (PMID 39968090, 2025). "In PCOS patients, Dingkun pill (DKP) or the combination of DKP and Diane-35 can lead to a decrease in the homeostasis model assessment of insulin resistance and an increase in the quantitative insulin sensitivity check index." (PMID 40842497, 2025). "Deregulated FGF23 and klotho are involved in impaired insulin signaling and insulin resistance through various potential mechanisms." (PMID 40237064, 2025). "From a metabolic perspective, aerobic exercise has a direct effect on the regulation of iron homeostasis by improving insulin sensitivity and reducing insulin resistance." (PMID 41413176, 2025). "In PCOS patients, insulin resistance is likely due to a diminished response to insulin in some metabolically active peripheral tissues, such as skeletal muscle and adipose tissue." (PMID 41595448, 2025). "Regarding flavonoids, it has been reported that quercetin has antidiabetic effects since it promotes insulin secretion, improves insulin resistance, and maintains glucose homeostasis." (PMID 40941053, 2025). "Over 90% of all cases of diabetes worldwide are caused by T2DM, which is the most prevalent kind of the disease and is brought on by insufficient insulin production or insulin resistance." (PMID 39942768, 2025). "HOMA-IR is a measure used to estimate insulin resistance, which is a condition where cells in the body become less responsive to insulin." (PMID 40822944, 2025).
Insulin resistance (continued). "The second is peripheral insulin resistance, in which free fatty acids (FFAs) and lipid metabolites (e.g., ceramides) inhibit insulin signaling in the adipocytes, myocytes, and hepatocytes to reduce glucose uptake and utilization." (PMID 41438998, 2025). "GLP-1 ameliorates insulin resistance by reducing body weight and augmenting the sensitivity of peripheral tissues to insulin." (PMID 40959695, 2025). "The pathogenesis of PTDM is similar to that of type 2 DM, sharing characteristics such as insulin resistance, hypertriglyceridemia, obesity, decompensated insulin release, hypertension, and low-grade inflammation." (PMID 40077085, 2025). "Diabetes is a chronic metabolic disease characterized by impaired insulin secretion from pancreatic β-cells or insulin resistance (IR) of body." (PMID 41227632, 2025). "The SGLT2i empagliflozin and DPP4i sitagliptin restore insulin sensitivity in HFD/STZ mice by decreasing IRS1 phosphorylation at Tyr632, associated with insulin resistance, and boosting AKT phosphorylation." (PMID 41146261, 2025). "The present study demonstrates that phosphatases carried by EVs from IR individuals induce systemic insulin resistance in mice by reducing the activation of insulin signalling in target tissues such as adipose tissue and liver." (PMID 39422717, 2025). "As ferroptosis progresses, β-cell viability declines, compounding insulin secretion deficits with peripheral insulin resistance and hyperglycemia." (PMID 40136648, 2025). "In T2D, GLP-1R agonists (GLP-1RA) improve obesity-related insulin resistance by enhancing β-cell insulin secretion and suppressing hepatic DNL." (PMID 40725208, 2025). "Under conditions of insulin resistance, β-cells are compelled to maintain glycemic control through compensatory hypersecretion of insulin." (PMID 41584842, 2025). "In patients with insulin-resistance, compared with insulin-sensitive subjects, the surface of the Beta cells is increased by 50%." (PMID 40943107, 2025). "Insulin Resistance and Hepatic Gluconeogenesis: The liver is a major site of insulin’s action (to suppress glucose production)." (PMID 40871736, 2025). "In a DHT-induced mouse model of PCOS, overexpression of adiponectin attenuated insulin resistance and glucose intolerance, while mice with adiponectin knockout showed decreased insulin sensitivity." (PMID 40013621, 2025). "Type 2 diabetes is characterized by a combination of peripheral insulin resistance and reduced secretion of insulin." (PMID 40275767, 2025). "In a glucose tolerance test performed at 11 months of age, APP/PS1/Hif-p4h-2gt/gt mice showed improved glucose clearance from blood compared with APP/PS1/Hif-p4h-2wt/wt, and they had lower fasting insulin levels and insulin resistance scores." (PMID 40609789, 2025). "Supplementation with omega-3 fatty acids has been shown to improve insulin sensitivity and reduce insulin resistance in women with PCOS." (PMID 40733002, 2025). "Adipose tissue secretes various cytokines and hormones, such as leptin and adiponectin, which affect the insulin signaling pathway, leading to insulin resistance." (PMID 40574814, 2025). "The probiotic supplementation also led to improvements in insulin sensitivity, as evidenced by a 34.12% reduction in homeostasis model assessment index of insulin resistance (HOMA‐IR)." (PMID 40613445, 2025). "In DHEA-induced PCOS rats, this combination significantly improved serum insulin levels, alleviating insulin resistance." (PMID 40234918, 2025). "Together, these findings suggest that habitual ingestion of SPs first induces insulin hypersecretion in response to glucose administration and subsequently induces insulin resistance." (PMID 40074175, 2025). "Our results showed that metformin and insulin treatment increased significantly the adipogenic capacity of preadipocytes only in insulin resistance." (PMID 41574186, 2025).
Insulin resistance (continued). "H. pylori infection induces systemic inflammation through the release of pro-inflammatory cytokines such as TNF-α, IL-1, and IL-6, which disrupt insulin signaling pathways and exacerbate insulin resistance." (PMID 40551731, 2025). "For instance, some of them are involved mainly in the impairment of insulin secretion, whereas others participate in the manifestation of insulin resistance." (PMID 39835172, 2025). "Most women in our cohort were premenopausal, with higher estrogen levels that provided vasodilatory, anti-inflammatory, and insulin-sensitizing effects, potentially buffering renal consequences of insulin resistance." (PMID 41010511, 2025). "Another important feature of PCOS is the dysregulation of glucose–insulin homeostasis leading to insulin resistance, compensatory hyperinsulinemia, and ultimately a greatly increased risk of developing of type 2 diabetes." (PMID 39636391, 2025). "However, insulin resistance in adipocytes causes lipolysis and lipotoxicity via the excessive release of free fatty acids and glycerol into the bloodstream, resulting in impaired insulin secretion through excessive lipid intake in tissues such as the liver, pancreas, and muscles." (PMID 40429507, 2025). "Thyroid hormones can enhance hepatic gluconeogenesis, increase lipolysis in peripheral adipose tissue, and induce insulin resistance through increased insulin secretion." (PMID 40170590, 2025). "Elevated in obesity, myostatin promotes WAT expansion and insulin resistance, whereas its genetic or pharmacologic inhibition reduces fat mass and enhances insulin sensitivity." (PMID 41002965, 2025). "Chronic kidney disease (CKD) results in insulin resistance, decreased insulin clearance, and inflammatory cytokine release." (PMID 41378064, 2025). "As for metabolism disorders, dysregulated glucose metabolism and insulin resistance stimulate insulin secretion, increasing hepatic triglyceride synthesis, which elevates plasma triglycerides and promotes NAFLD progression." (PMID 40746546, 2025). "This synergizes with their insulin-sensitizing effects (via PTP1B inhibition) to overcome insulin resistance." (PMID 40430501, 2025). "Since insulin resistance and hyperinsulinemia are major contributors to type 2 diabetes and its consequences, the improvement in insulin dynamics looks clinically significant." (PMID 41011232, 2025). "At the same time, insulin resistance can lead to hypertension because insulin affects vasomotor function." (PMID 40422894, 2025). "SGLT-2is did not influence the secretion of C-peptide and lowered blood glucose levels independently of insulin, thereby reducing insulin resistance and improving β-cell function." (PMID 41252382, 2025). "Although current research indicates that quinones exhibit potential in regulating insulin signaling pathways, improving insulin resistance, and suppressing inflammatory responses, their specific mechanisms of action remain incompletely understood." (PMID 39942768, 2025). "Chronic inflammation in PsA, characterized by enhanced levels of cytokines and adipokines, impairs the insulin signaling pathway, thus leading to insulin resistance." (PMID 40137170, 2025). "Fasting serum insulin, a marker of insulin resistance, was one of our study's strongest predictors of DR." (PMID 40778361, 2025). "Insulin and GH exert reciprocal influences: while GH promotes lipolysis and insulin counteracts this effect, chronic hyperinsulinemia and insulin resistance can impair GH signaling." (PMID 41282298, 2025). "This review emphasizes how oxidative and nitrosative distress disrupt insulin signaling through protein and lipid oxidation, mitochondrial fragmentation, and inflammatory pathways, ultimately driving muscle dysfunction and insulin resistance." (PMID 41226411, 2025). "Rats fed a high-fat diet (HFD) show early insulin resistance, which is typified by weight gain, increased fat accumulation, and compromised insulin and glucose regulation." (PMID 40943103, 2025).